HOXD11 (homeobox D11)
Description:
Sequence-specific transcription factor which is part of a developmental regulatory system that provides cells with specific positional identities on the anterior-posterior axis.
Synonyms: HOX4F; HOX4
Tractability: No criterion of Open Targets' tractability assessment is met for any kind of drug.
Gene: Protein-coding gene on chromosome 2 (176,104,216 to 176,109,754, forward strand). Ensembl gene ENSG00000128713.
Subcellular location: Nucleus
Subcellular location (Human Protein Atlas): Nucleoplasm
Pathways (Reactome):
Developmental Biology: Formation of the ureteric bud
Gene Ontology:
Molecular function: sequence-specific double-stranded DNA binding; DNA-binding transcription factor activity, RNA polymerase II-specific; RNA polymerase II cis-regulatory region sequence-specific DNA binding; DNA binding
Biological process: branching involved in ureteric bud morphogenesis; dorsal/ventral pattern formation; embryonic skeletal joint morphogenesis; regulation of transcription by RNA polymerase II; regulation of DNA-templated transcription
Cellular component: nucleoplasm; chromatin; nucleus
Genetic constraint (gnomAD): Loss-of-function variants: 16 observed, 17.03 expected, observed/expected ratio (o/e) 0.94, 90% interval 0.63 to 1.42. The synonymous counts are far from expectation, so gnomAD's model fits this gene poorly and the ratio says little. Missense variants: 523 observed, 374.45 expected, observed/expected ratio (o/e) 1.4, 90% interval 1.3 to 1.5. Synonymous variants: 242 observed, 169.9 expected, observed/expected ratio (o/e) 1.42, 90% interval 1.28 to 1.58.
Homologues: Orthologues: chimpanzee HOXD11 (99% identical), macaque HOXD11 (97% identical), rabbit HOXD11 (96% identical), pig HOXD11 (95% identical), mouse Hoxd11 (93% identical), rat Hoxd11 (93% identical), tropical clawed frog hoxd10 (52% identical), zebrafish hoxd11a (45% identical), zebrafish hoxc11b (36% identical). Paralogues in human: HOXA11 (48% identical), HOXC11 (40% identical), HOXA13 (20% identical), HOXD10 (20% identical), HOXC13 (19% identical), HOXB9 (18% identical), HOXB13 (17% identical), HOXC10 (17% identical), HOXD13 (17% identical), HOXA10 (17% identical), HOXD9 (17% identical), HOXC9 (16% identical), and 30 more.
Diseases named in the same sentence as HOXD11 in open-access papers:
HOXD11 is named in the same sentence as 33 diseases in open-access papers, as found by Europe PMC text mining. Sharing a sentence is not in itself a finding about the gene and the disease. The quoted sentences say what the papers report.
Ewing sarcoma (6 papers, 2017 to 2022). A small round cell tumor that lacks morphologic, immunohistochemical, and electron microscopic evidence of neuroectodermal differentiation. "Notably, all but one of these (HOXD4) have previously been implicated in the promotion of cancer, and HOXD11 has specifically been demonstrated to be disease-promoting in Ewing Sarcoma." (PMID 30237855, 2018). "We recently reported that high expression of posterior Homeobox D gene cluster (HOXD) genes is a hallmark of Ewing sarcoma and that ectopic expression of EWS-FLI1 in neural crest-derived MSCs hijacks normal epigenetic regulation of HOXD10, HOXD11, and HOXD13." (PMID 30845695, 2019). "In addition, knockdown of HOXD13, and also of HOXD10 and HOXD11, results in loss of tumorigenicity, verifying the identity of posterior HOXD genes as critical oncogenes in Ewing sarcoma." (PMID 27888797, 2017). "HOXD11 may also change cell growth, clonality, and metastatic potential in Ewing sarcoma." (PMID 36251702, 2022). "The research of ewing sarcoma exhibited that HOXD11 and HOXD13 promoted growth and metastasis of ewing sarcoma." (PMID 32557953, 2020). "Human Ewing sarcoma tumors over-express HOXD10, HOXD11, and HOXD13 and maintenance of the tumorigenic Ewing sarcoma state requires continued high-level expression of HOXD13." (PMID 30845695, 2019). "HOXD10, HOXD11 and HOXD13 play essential roles in maintaining the oncogenic phenotype of Ewing sarcoma proliferation, invasion and metastasis (current study and Ref." (PMID 27888797, 2017). "In the context of human Ewing sarcoma, knockdown of HOXD10, HOXD11, and HOXD13 all independently impaired the growth and invasive properties of tumor cells, demonstrating that despite the marked over-expression of HOXD13, all members of the posterior HOXD cluster contribute to human tumorigenesis." (PMID 30845695, 2019). "We and others have shown that the posterior HOXD genes, HOXD9, HOXD10, HOXD11, and HOXD13 are overexpressed by Ewing sarcoma and that the promoters of these genes are devoid of the repressive H3K27me3 mark and highly enriched with the MLL-mediated H3K4me3 mark." (PMID 27888797, 2017).
glioma (6 papers, 2021 to 2025). A benign or malignant brain and spinal cord tumor that arises from glial cells (astrocytes, oligodendrocytes, ependymal cells). "HOXD11, as an independent risk factor, reduces the overall survival of glioma patients and has diagnostic value for the prognosis of glioma." (PMID 33614284, 2021). "The results suggested that high expression levels of HOXD11 was significantly related to poor prognosis as a risk factor for glioma (p < 0.001; HR = 1.550; 95% CI [1.456–1.650])." (PMID 33614284, 2021). "To clarify the diagnostic value of highly expressed HOXD11 for glioma prognosis, we plotted the receiver operating characteristic (ROC) curve based on the sequencing data of glioma patients from CGGA and TCGA databases." (PMID 33614284, 2021). "Many HOMEOBOX (HOX)-related genes (HOXD11, HOXD9, HOXC10, HOXC11, HOXC6, HOXB3, HOXA2, HOXA1) were associated with a glioma grade and significantly overexpressed in GIV (Wilcoxon rank-sum and BH padj < 0.05)." (PMID 36850002, 2023). "In the regulation of transcription, HOXD11 overexpression participated in head and neck squamous cell carcinoma, laryngeal squamous cell carcinoma, glioma and hemangioblastoma by promoting cell proliferation, cell migration and angiogenesis." (PMID 36151071, 2022). "This study aimed to explore the relationship between HOXD11 and gliomas by combining bioinformatics methods with basic experimental validation." (PMID 33614284, 2021). "To clarify the relationship between high expression of HOXD11 and the clinical and prognosis of glioma patients, we conducted further studies using glioma sequencing data and relevant clinical information from CGGA database." (PMID 33614284, 2021). "The Kaplan–Meier method was used to verify that the increase of HOXD11 expression level can indeed reduce the overall survival time of glioma patients." (PMID 33614284, 2021). "To verify the effect of HOXD11 on malignant biological behavior of glioma cell lines, we conducted a series of phenotypic experiments." (PMID 33614284, 2021). "A series of bioinformatic analysis methods were used to confirm the relationship between HOXD11 expression and overall survival and clinical molecular characteristics of patients with glioma." (PMID 33614284, 2021). "We found that HOXD11, as a novel carcinogenic gene in gliomas, expression levels were significantly higher in gliomas than that in non-tumor brain tissues." (PMID 33614284, 2021). "In addition, high expression of HOXD11 may be associated with poor prognosis in glioma patients." (PMID 33614284, 2021). "MTT assay, colony formation assay, wound-healing assay, immunofluorescence staining, flow cytometry and western blotting were used to detect the effect of HOXD11 on the biological behavior of glioma cell line U251." (PMID 33614284, 2021). "As another limitation, the mechanism whereby high expression of HOXD11 leads to poor prognosis in glioma patients was indirectly revealed by functional enrichment analysis via GSEA." (PMID 33614284, 2021). "This study only provides a clue to lead more researchers to pay attention to the role of HOXD11 in glioma." (PMID 33614284, 2021). "Here, we examined the relationship between high or low expression level of HOXD11 and the prognosis and clinical features of glioma using bioinformatics approaches." (PMID 33614284, 2021). "Further indirect analysis by Gene Set Enrichment Analysis (GSEA) was used to reveal the mechanism of action of HOXD11 in gliomas." (PMID 33614284, 2021). "The relationship between overall survival and the expression level of HOXD11 in patients with gliomas was explored by Kaplan–Meier survival analysis." (PMID 33614284, 2021). "Furthermore, HOXD11 can promote the malignant behavior of glioma cells as an oncogene by participating in the regulation of cell cycle signaling pathways." (PMID 37091145, 2023).
glioma (continued). "In addition, the overexpression of HOXD11 was a poor prognostic biomarker in head and neck squamous cell carcinoma and gliomas by promoting tumor proliferation and invasion." (PMID 36151071, 2022). "HOXD11 may be used as a candidate biomarker for the clinical application of targeted drugs and prognostic assessment therapy for glioma." (PMID 36213580, 2022). "Finally, a variety of experimental methods have been used to confirm that HOXD11 can promote the malignant behavior of glioma cells as an oncogene by participating in the regulation of cell cycle signaling pathways." (PMID 33614284, 2021). "By analyzing the sequencing data of glioma samples and matching clinical information from multiple sources, the results showed that HOXD11 could be an independent prognostic factor for glioma and had certain diagnostic value." (PMID 33614284, 2021). "To clarify the impact of HOXD11 expression level on the prognosis of gliomas of different molecular subtypes, we divided the samples into three groups (IDH mutation with 1p19q codeletion, IDH mutation without 1p19q codeletion and IDH wild type) for survival analysis." (PMID 33614284, 2021). "To clarify how HOXD11 plays a role in the pathological process of glioma, we performed GSEA analysis to predict the cell signaling pathways that HOXD11 may participate in." (PMID 33614284, 2021). "Therefore, we believe that highly expressed HOXD11 is involved in the pathological process of glioma by affecting the proliferation and migration of glioma cells." (PMID 33614284, 2021). "First, we used siRNA to interfere with the expression level of HOXD11 in glioma cell U251." (PMID 33614284, 2021). "Through GSEA analysis, we predicted that highly expressed HOXD11 may participate in the pathological process of glioma through a variety of cancer-related cell signaling pathways." (PMID 33614284, 2021). "Therefore, other specific mechanisms of HOXD11 affecting glioma need to be further verified by other research." (PMID 33614284, 2021). "This study found that compared with normal controls, the expression level of HOXD11 was higher in glioma samples at the cell and tissue level, and may be related to the poor overall survival of patients with glioma." (PMID 33614284, 2021). "Therefore, we have sufficient reason to confirm that HOXD11 can be a valuable biomarker for targeted treatment of glioma patients." (PMID 33614284, 2021). "Finally, it is worth emphasizing that the knockdown of HOXD11 can inhibit the proliferation and migration of U251 glioma cells." (PMID 33614284, 2021). "RT-qPCR was used to verify the change of expression level of HOXD11 in glioma cells and tissues." (PMID 33614284, 2021). "HOXD11 may be used as a candidate biomarker for the clinical application of targeted drug and prognostic assessment treatment of glioma." (PMID 33614284, 2021). "Finally, we confirmed that the knockout of HOXD11 can inhibit the proliferation and invasion of U251 glioma cells, and change the biological behavior of tumor cells by preventing the progression of cell cycle." (PMID 33614284, 2021). "To explore the effect of HOXD11 on the cell cycle of glioma cell U251, we performed flow cytometry." (PMID 33614284, 2021). "Therefore, HOXD11 could be used as a candidate biomarker for molecular therapy and prognostic evaluation of patients with glioma." (PMID 33614284, 2021). "The expression level of HOXD11 increases as the WHO grade and age of the glioma increases (p < 0.001)." (PMID 33614284, 2021). "Among the seven key genes (HOXD11, HOXC9, HOXC6, HOXA3, FBXO39, OTP, and HMGA2) consistently detectable in both normal astrocyte cell lines (SVG-P12) and glioma cell lines (U87, U251, LN229), tumor cell lines exhibited significantly upregulated expression compared to normal cell lines." (PMID 41049291, 2025). "Homeobox D11 (HOXD11) plays an important role in a variety of cancers, but its precise role in gliomas remains unclear." (PMID 33614284, 2021).
glioma (continued). "The results of our study indicate that HOXD11 is highly expressed in glioma samples relative to non-tumor brain tissue." (PMID 33614284, 2021). "However, as far as we know, there is no report on the relationship between HOXD11 and glioma." (PMID 33614284, 2021). "In addition, HOXD11 may be involved in cancer-related cell signaling pathways, such as cell cycle, DNA replication, focal adhesion, and ECM receptor interaction, and thereby affect the malignant progression of glioma by participating in the regulation of the cell cycle." (PMID 33614284, 2021).
ovarian carcinoma (5 papers, 2012 to 2025). A malignant neoplasm originating from the surface ovarian epithelium. "HOXD11 has been associated with several malignancies in recent years, including laryngeal squamous cell carcinoma, ovarian cancers, and head and neck cancer." (PMID 37091145, 2023). "Multiple types of mutations and changes in expression in HOXD11 have been observed in lung cancer, Oral Squamous Cell Carcinoma, prostate cancer, ovarian cancer, and Head and Neck Squamous Cell Carcinoma." (PMID 36251702, 2022). "This gene seems to be silenced in breast cancer, ovarian cancer and melanoma, suggesting that a specific methylation pattern of a group of genes, involving HOXD11, may be useful as diagnostic and prognostic biomarkers." (PMID 22227861, 2012). "Similarly, high methylation levels of HOXD11 are also regarded as poor indicators in breast cancer and ovarian cancer." (PMID 36151071, 2022).
head and neck cancer (4 papers, 2014 to 2023). A primary or metastatic malignant neoplasm affecting the head and neck. "POU2F1 activity regulates HOXD10 and HOXD11 to promote proliferative and invasive phenotypes in head and neck cancer." (PMID 36213580, 2022). "For instance, in head and neck cancer, POU2F1 can bind to the promoters of HOXD10 and HOXD11 to activate their transcription, thus promoting tumor progression." (PMID 34257651, 2021).
oral cancer (4 papers, 2014 to 2025). "In contrast, HOXA7, HOXA10, HOXB7, HOXC6, HOXC10, HOXD10, and HOXD11 were consistently upregulated in potentially malignant oral lesions as they advanced to oral cancer." (PMID 41477365, 2025). "HOXA7, HOXA10, HOXB7, HOXC6, HOXC10, HOXD10, HOXD11 showed consistent upregulation in the potentially malignant oral lesions through their progression to oral cancer, which indicated the posterior prevalence of the HOX genes during cancer progression." (PMID 35710803, 2022). "Overall our results suggest that HOXD10 and HOXD11 act as oncogenes in oral cancer, whereas previous reports have indicated that they act as tumor suppressors." (PMID 25301728, 2014).
head and neck squamous cell carcinoma (3 papers, 2017 to 2022). A squamous cell carcinoma that arises from any of the following anatomic sites: lip and oral cavity, nasal cavity, paranasal sinuses, pharynx, larynx, and salivary glands. "According to Sharpe and colleagues 23, HOXD10 and HOXD11 are expressed at high levels in head and neck squamous cell carcinoma, which corresponded to our results." (PMID 28745433, 2017).
neuroblastoma (3 papers, 2016 to 2022). Neuroblastoma (NB) is the most common solid, extracranial childhood tumor. "Furthermore, qRT-PCR confirmed a significantly lower expression of HOXD10, HOXD11 and HOXD13 in neuroblastoma and osteosarcoma." (PMID 27363011, 2016). "Similarly, several HOX genes including HOXD11 and HOXD12 which are known to be ATRA responsive in neuroblastoma cells, and to be able to induce growth arrest and differentiation in these cells, were significantly induced in WT but to a lesser degree or were not induced in BKO98 cells." (PMID 35831557, 2022). "Interestingly, only HOXD10, HOXD11 and HOXD13 of the homeobox loci, normally involved in bone formation and ossification pattern of bones, were significantly up-regulated in ES in comparison to neuroblastoma, normal and fetal tissue." (PMID 27363011, 2016).
bladder cancer (1 paper, 2023). "In addition, HOXD11 expression was detected in 57% of bladder cancer tissues." (PMID 37627900, 2023). "Four genes (HOXC4, HOXC5, HOXC6, and HOXC11) located at the HOX C locus as well as one gene (HOXD11) located at the HOX D locus were not expressed in normal bladder tissues but expressed in most bladder cancer tissues." (PMID 37627900, 2023).
cystic teratoma (1 paper, 2024). "In summary, amplifications of EVX2, HOXD13, HOXD12, HOXD11, HOXD10, and HOXD9 on 2q31.1, NDUFV1 on 11q13.2, and RPL10, SNORA70, DNASE1L1, TAZ, ATP6AP1, and GDI1 on Xq28 were found in all nine mature cystic teratomas in this study." (PMID 38907278, 2024). "The most interesting findings of this study are amplifications of EVX2, HOXD13, HOXD12, HOXD11, HOXD10, and HOXD9 on a 41.6 kb segment of 2q31.1 in all nine mature cystic teratomas." (PMID 38907278, 2024).
dysplasia (1 paper, 2018). A usually neoplastic transformation of the cell, associated with altered architectural tissue patterns. "The HOXA11/HOXD11 genes are particularly intriguing candidates as potential upstream regulators of SHOX since their mutation in mice causes zeugopodal truncations similar to that of Langer mesomelic dysplasia patients." (PMID 30250174, 2018).
gastric cancer (1 paper, 2012). A primary or metastatic malignant neoplasm involving the stomach. "In gastric cancer, HOXD11 is expected to exert a regulating role in αV integrin gene, even if its expression pattern in tumors contrasts with the functions that this protein seems to have in neoplastic cells, mainly promoting cell migration and survival." (PMID 22227861, 2012). "On the other hand, HOXD11 is transcribed in gastric carcinoma in an abnormal manner suggesting an important role in the development of this disease." (PMID 22227861, 2012).
lymph node metastasis (1 paper, 2022). "More importantly, overexpression of HOXD11 was associated with advanced disease, such as T grade, lymph node metastasis and extranodal extension (ENE), indicating the clinical significance of poor outcomes." (PMID 36151071, 2022). "In summary, we explored the available oncogene HOXD11, which is overexpressed in PSCC and is associated with lymph node metastasis and poor patient prognoses." (PMID 36151071, 2022). "In this study, we explored the available oncogene HOXD11, which is overexpressed in PSCC and is associated with lymph node metastasis and poor patient prognoses." (PMID 36151071, 2022). "In addition, IHC was performed with an mPSCC patient with retroperitoneal lymph node metastases, and we found that HOXD11 was strongly expressed in tumors, especially in metastatic lesions." (PMID 36151071, 2022).
mouth neoplasms (1 paper, 2022). "Two other posterior HOX genes, HOXD10, and HOXD11 were shown to be associated with the mouth neoplasm based on the semantic analysis performed using DO." (PMID 35710803, 2022).
osteoarthritis (1 paper, 2024). A noninflammatory degenerative joint disease occurring chiefly in older persons, characterized by degeneration of the articular cartilage, hypertrophy of bone at the margins and changes in the synovial membrane. "Whether the HOXD11 has a related signaling pathway and whether the pathway is related to osteoarthritis, it needs further research on the relationship between the HOXD11 and the signaling pathway." (PMID 38308324, 2024).
prostate tumors (1 paper, 2011). "Several transcription factors, including NKX3-1, HOXB13, HOXC6, HOXD11 and HOXD13, were also found to have deregulated expression in the stromal reaction to invasive prostate tumors." (PMID 21611158, 2011).